PLAG1 (PLAG1 zinc finger)
Diseases named in the same sentence as PLAG1 in open-access papers (continued):
Sharing a sentence is not in itself a finding about the gene and the disease.
Obesity (7 papers, 2020 to 2025). Accumulation of substantial excess body fat. "Studies reported that the expression level of fat mass and obesity associated gene (FTO) and pleomorphic adenoma gene 1 (PLAG1) genes associated with obesity was significantly related to the concentration of leptin." (PMID 35498804, 2022). "The analysis of the expression of PLAG1 gene also showed a significantly higher expression in the obesity group compared to the control group (89.88 ± 1.32 vs. 65.8 ± 1.17, FC = 1.37, p(B-H) = 0.036)." (PMID 34063412, 2021). "Concentrations of IGF-2, the key PLAG1 target gene, were shown to be higher in children with obesity compared to the control group, and were found to be associated with increased leptin levels in adult, normal-weight patients." (PMID 34684585, 2021). "Another example is an association for PLAG1, which was found to be over-expressed in children with obesity compared to children without obesity." (PMID 40321767, 2025). "The PLAG1 gene is important in modulating the activity of metabolic processes, so it may have a potential impact on the occurrence of obesity in the pediatric population, which has been recently observed." (PMID 34063412, 2021). "In addition to the well-described role of PLAG1 as a driver of carcinogenesis, a possible novel aspect of its function, namely affecting the development of obesity, is currently coming to light." (PMID 34063412, 2021). "Therefore, the aim of our study was to analyze the genome expression and methylation of FTO and PLAG1 genes in children with obesity." (PMID 34063412, 2021). "Literature analysis brings to the conclusion that certain metabolic parameters commonly disrupted in obesity could be affected by changes in PLAG1 expression." (PMID 34063412, 2021). "PLAG1 may be involved in certain aspects of obesity pathogenesis." (PMID 34684585, 2021). "Many studies, also in the pediatric population, focus on single nucleotide polymorphisms (SNPs) in genes with a well-described relationship with obesity, such as FTO, or genes, whose role in obesity is recently gradually being discovered, as the PLAG1 gene." (PMID 34063412, 2021). "The significant genes in GWAS results (CALCR, PLAG1, INSIG2, PPARG, BMP5, S100A10) also have been identified to have relationship with growth performance and obesity of adipose tissue for pig and cattle." (PMID 33264312, 2020). "Therefore, we focus on the relationship between obesity and the degree of methylation of FTO (FTO alpha-ketoglutarate dependent dioxygenase) and PLAG1 (pleomorphic adenoma gene 1 zinc finger) genes." (PMID 34063412, 2021).
Uterine leiomyoma (7 papers, 2014 to 2024). The presence of a leiomyoma of the uterus. "Recently, uterine leiomyomas with HMGA2 aberrations were shown to display highly significant up-regulation of PLAG1." (PMID 28591699, 2017). "The results presented herein point to HMGA2 as an upstream regulator of PLAG1 and are additionally confirmed by the correlation between the expressions of both genes in uterine leiomyomas." (PMID 24516594, 2014). "The results of this study imply that HMGA1 and PLAG1 rearrangements are likely to explain a small proportion of uterine leiomyomas with no mutations in the well‐established driver genes." (PMID 35822448, 2023). "A strong correlation of PLAG1 and HMGA2 expression was also detected in a number of thyroid carcinomas and uterine leiomyomas and cell culture experiments led to the conclusion that HMGA2 is an upstream activator of PLAG1." (PMID 25923053, 2015). "To further analyze the relationship between these two genes, we also quantified the PLAG1 expression in 32 uterine leiomyomas (UL) with as well as without 12q14 rearrangements." (PMID 24516594, 2014). "While it has been suggested that alteration of HMGA2 is considered to be the initial step leading to significant upregulation of PLAG1, the role of RAD51B should not be overlooked, as it is also important in uterine leiomyoma development." (PMID 37466765, 2024).
acute myeloid leukemia (6 papers, 2016 to 2025). Acute myeloid leukemia (AML) is a group of neoplasms arising from precursor cells committed to the myeloid cell-line differentiation. "Abnormal misexpression of both PLAG1 and PLAGl2 appeared in acute myeloid leukemia-induced amphotropic murine leukemia virus (MLV) strain 4070A48." (PMID 31784561, 2019). "For example, one shared downstream target of PFAs and DMGs with PRC2-impaired tumors is the zinc-finger transcription factor pleomorphic adenoma gene 1 (PLAG1), which is de-repressed in EZH2-mutated acute myeloid leukemia (AML)." (PMID 34762160, 2022). "PLAGL2 was shown to upregulate IGF2 expression levels in hematopoietic progenitors of acute myeloid leukemia and IGF2 harbors eight PLAG1/PLAGL2 consensus binding sites." (PMID 36437415, 2023). "In the combined analysis of GTEX and TCGA data, PLAG1 highly expressed in tumors in pheochromocytoma and paraganglioma (PCPG), while its expression level in the bone marrow or peripheral blood of acute myeloid leukemia (LAMA) patients is lower than that in healthy controls." (PMID 40276502, 2025).
leiomyoma (6 papers, 2014 to 2024). A well-circumscribed benign smooth muscle neoplasm characterized by the presence of spindle cells with cigar-shaped nuclei, interlacing fascicles, and a whorled pattern. "We identified chromosomal rearrangements targeting either HMGA2, HMGA1, or PLAG1 in all 16 tumors, demonstrating that it is possible to detect chromosomal driver alterations in archival leiomyoma specimens as old as 18 years." (PMID 35822448, 2023). "In line with the 3′RNA‐sequencing results, the structural variant analysis detected an HMGA2 rearrangement in eight leiomyomas, an HMGA1 rearrangement in four leiomyomas, and a PLAG1 rearrangement in four leiomyomas." (PMID 35822448, 2023). "PLAG1 rearrangements are common in other benign mesenchymal tumors, but their role in leiomyomas remains ambiguous." (PMID 35822448, 2023). "Taking the FISH and expression analyses together, PLAG1 seems to be targeted by 8q aberrations in leiomyomas of deep soft tissue." (PMID 28591699, 2017). "Significant upregulation of PLAG1 was described in HMGA2 subtype of leiomyoma." (PMID 37466765, 2024). "In addition to rearrangements of HMGA1, HMGA2, and PLAG1, we identified biallelic loss of DEPDC5 in one leiomyoma with an HMGA2 rearrangement and in another leiomyoma with an HMGA1 rearrangement." (PMID 35822448, 2023). "Unlike HMGA2 rearrangements, HMGA1 and PLAG1 rearrangements are rare in leiomyomas and may co‐occur with MED12 mutations, suggesting that they are secondary events related to tumor progression." (PMID 35822448, 2023). "However, none of the samples with an HMGA1 or PLAG1 rearrangement in this study harbored an alteration in a well‐established leiomyoma driver gene and all displayed expression features associated with leiomyomas of the HMGA2‐subtype." (PMID 35822448, 2023). "One of these clusters consisted of 16 leiomyomas that showed high expression of HMGA1 and the other consisted of 12 leiomyomas that displayed exceptionally high expression of PLAG1, but low expression of both HMGA1 and HMGA2." (PMID 35822448, 2023). "To conclude, we have here confirmed that leiomyomas with an HMGA2, HMGA1, or PLAG1 rearrangement share multiple molecular features, including similar gene expression patterns and shared translocation partners." (PMID 35822448, 2023). "In the leiomyomas with 12q rearrangements, both HMGA2 and PLAG1 were expressed whereas in the tumors with 8q aberrations, only PLAG1 was expressed." (PMID 28591699, 2017). "Interestingly, we identified a subset of tumors to display expression features typically seen in leiomyomas with an HMGA2 rearrangement, including PLAG1 overexpression." (PMID 35822448, 2023). "As expected, we detected significant upregulation of PLAG1 in leiomyomas of the HMGA2 and FH subtypes, but not in leiomyomas of the MED12 subtype." (PMID 33352722, 2020).
myoepitheliomas (5 papers, 2017 to 2022). "Other subgroups of myoepithelial tumors of soft tissue are associated with alternative genetic aberrations such as rearrangements of other genes (e.g., PLAG1) or homozygous deletion of the INI1/SMARCB1 gene, while in a large proportion, the genetic background is not yet known." (PMID 31049020, 2019). "Several mutations have been identified, including PLAG1 (pleiomorphic adenoma gene 1 protein) or EWSR1 (Ewing sarcoma breakpoint region 1) gene rearrangements, also found in myoepitheliomas, similar to pleomorphic adenomas." (PMID 34064849, 2021). "Myoepithelial neoplasms (MN) are rare and not well-circumstanced entities displaying a heterogeneous spectrum of genetic abnormalities, including EWSR1, FUS and PLAG1 rearrangements." (PMID 28947952, 2017).
Silver-Russell syndrome (5 papers, 2020 to 2025). Silver-Russell syndrome is characterized by growth retardation with antenatal onset, characteristic facies and limb asymmetry. "PLAG1 deletion is associated with Silver-Russell syndrome, which is characterized by fetal growth restriction and facial dysmorphology." (PMID 40276502, 2025). "Rearrangement of HMGA2 is suggested to drive tumorigenesis by the (dis-)regulatory effect of the HMGA2 protein on PLAG1 and IGF2 expression, a suggestion based on the downregulation of IGF2 expression in patients with Silver-Russel syndrome." (PMID 40338436, 2025).
adenoid cystic carcinoma (4 papers, 2017 to 2025). A malignant tumor arising from the epithelial cells. "In fact, demonstrating a rearrangement of MYB, MYBL1, PLAG1, HMGA2, NTRK3, and a BRAF mutation in the appropriate morphological context is diagnostic of adenoid cystic carcinoma, cutaneous mixed tumor, secretory carcinoma, syringocystadenoma papilliferum, and tubular adenoma." (PMID 35158743, 2022). "Although PLAG1 expression is not useful for distinguishing between pleomorphic adenoma and carcinoma ex pleomorphic adenoma, it may still aid cytopathologists in differentiating pleomorphic adenoma from other basaloid SUMP tumors, such as basal cell adenoma or adenoid cystic carcinoma." (PMID 40326164, 2025).
gastric cancer (4 papers, 2023 to 2025). A primary or metastatic malignant neoplasm involving the stomach. "Thus, circPOFUT1 promoted the proliferation, migration, invasion, and autophagy-related chemotherapy resistance of gastric cancer by activating PLAG1 and ATG12 through miR-488-3p binding." (PMID 40936702, 2025). "In addition, the competing endogenous RNAcircPOFUT1 can relieve the inhibitory effect of PLAG1 by binding to miR-488-3p, and PLAG1 regulates ATG12 expression to enhance tumor cell autophagy, thereby increasing the resistance of gastric cancer cells to cisplatin." (PMID 40276502, 2025).
myoepithelial carcinoma (4 papers, 2019 to 2024). "In addition to the CTNNB1–PLAG1 fusion, there are at least eight additional known PLAG1 fusions in pleomorphic adenomas and myoepithelial carcinoma ex-pleomorphic adenomas that lead to ectopic overexpression of wild-type PLAG1 proteins." (PMID 31426421, 2019). "Fusion transcripts involving PLAG1 as 3′ partner, frequently seen in SGC arising from pleomorphic adenomas (CXPA), were detected in SDC (n = 7), myoepithelial carcinoma (n = 1) and a case with mixed PLGA/myoepithelial histology." (PMID 36077692, 2022).
adipose tissue tumors (3 papers, 2014 to 2023). "Because of the apparent relationship of HMGA2 and PLAG1 in the molecular pathogenesis of salivary gland adenomas and adipose tissue tumors, we also quantified and compared the expression of HMGA2 and PLAG1 mRNA in thyroid adenomas as well as in papillary and follicular thyroid carcinomas." (PMID 24516594, 2014). "These genetic abnormalities in PLAG1 help distinguish LPBs from other lipomatous neoplasms, although a subset of LPBs express polysomy of chromosome 8 or HMGA2 gene rearrangements with or without PLAG1 involvement." (PMID 38012697, 2023).
breast carcinoma (3 papers, 2015 to 2022). "The genes that overlapped with the three other FST peaks were FANCA, a candidate for breast cancer susceptibility, PLAG1 that is associated with stature and body weight, and BIN1 that is associated with Alzheimer’s disease." (PMID 26089079, 2015). "A computational pipeline has recently been developed to identify transcribed enhancers in breast cancer and demonstrated that TFs such as FOSL1 and PLAG1 play key roles in regulating the activities of TNBC enhancers." (PMID 34718356, 2022). "Besides, AXIN2, PLAG1, GPC3, DICER1 are not connected with any breast cancer genes." (PMID 31760937, 2019).
breast neoplasm (3 papers, 2020 to 2026). A benign or malignant neoplasm of the breast parenchyma. "Our findings not only highlight the diagnostic complexity of this rare breast neoplasm, which is prone to misclassification, but also expand the known genetic landscape of PA through the discovery of the novel PLAG1::FTO fusion." (PMID 41869656, 2026). "We observed that the transcription factors EN1, SOX9 and PLAG1 were significantly higher expressed in basal-like breast tumours (which include approximately 80% TNBC), compared to the other breast tumour subtypes." (PMID 41505030, 2026). "In addition, EN1, SOX9 and PLAG1 genes were significantly higher expressed in basal-like breast tumours." (PMID 41505030, 2026). "Our findings suggest that the assessment of rearrangements involving PLAG1 or HMGA2 in breast PAs, and of MAML2 rearrangements in breast MECs, might be used as ancillary tools to aid in the diagnosis of these rare breast tumors." (PMID 32550265, 2020).
embryonal tumor (3 papers, 2022 to 2025). "Here, we use DNA methylation profiling in combination with copy number, RNA-seq, and histological analysis to characterize and classify a novel group of CNS embryonal tumors harboring PLAG1 gene fusions (n=12)." (PMID 40751809, 2025). "The question if treatment regimens used for other embryonal tumors as intensified chemotherapy or CSI are the most beneficial treatment approaches in the case of a PLAG1-fused tumor remains to be clarified." (PMID 40751809, 2025). "To conclude, we report, for the first time, two embryonal tumors with PLAG1 fusions sharing clinico-radiological, histopathological, immunohistochemical, and epigenetic similarities to CNS embryonal tumors with PLAG-family amplification." (PMID 37870637, 2023). "In addition, embryonal tumors with multilayered rosettes (ETMR) express high levels of PLAG1, but the regulatory mechanism of PLAG1 expression in these tumors is still unclear." (PMID 34762160, 2022). "The original histopathologic diagnoses comprised low-grade glioma (LGG) (n = 1), embryonal tumor NOS (n = 2), high-grade neuroepithelial tumor (HGNET) with PLAG1 fusion (n = 1), primitive neuroectodermal tumor (PNET) (n = 1), supratentorial ependymoma (n = 4), and oligodendroglioma (n = 1)." (PMID 40751809, 2025). "Here, we report two cases, classified as being part of the “embryonal tumor with PLAG-family amplification” methylation class (MC), that did not have a PLAG-family amplification but instead harbored a PLAG1 fusion." (PMID 37870637, 2023). "Three cases out of 31 (9.7%) of DNA-methylation based embryonal tumors with PLAGL1/2 did not harbor any amplifications of these genes, and to our knowledge, PLAG1 fusions were not explored." (PMID 37870637, 2023).
hepatocellular carcinoma (3 papers, 2021 to 2024). A malignant tumor that arises from hepatocytes. "The pro-tumor effects of KPNA2 have also been validated in hepatocellular carcinoma (HCC) where KPNA2 mediates the nuclear import of the transcriptional factor pleomorphic adenoma gene 1 (PLAG1) protein." (PMID 33731128, 2021). "Additionally, PLAG1 overexpression hinders the therapeutic effects of sorafenib on hepatoma cells." (PMID 38745179, 2024). "PLAG1, regulated by the lncRNA PVT1, confers resistance to sorafenib-induced ferroptosis in hepatocellular carcinoma by upregulating GPX4 and maintaining redox homeostasis." (PMID 39315094, 2024). "Utilizing data from the TCGA database, we developed ceRNETs specific to hepatocellular carcinoma, revealing PVT1 as a potential ceRNA for PLAG1 through identification of central network nodes." (PMID 38745179, 2024). "Similar to our findings, the nuclear import of PLAG1 has been illustrated to be aided by KPNA2 in hepatocellular carcinoma (HCC) and PLAG1 seemed to be partly responsible for the functional role of KPNA2 in HCC." (PMID 33731128, 2021).
leiomyosarcoma (3 papers, 2022 to 2025). An uncommon, aggressive malignant smooth muscle neoplasm, usually occurring in post-menopausal women. "Detection of PLAG1 fusions, using fluorescence in situ hybridization (FISH) or PLAG1 IHC, may aid in distinguishing myxoid leiomyosarcoma from other histologically similar tumors." (PMID 41463261, 2025).
leukemia (3 papers, 2012 to 2023). A malignant (clonal) hematologic disorder, involving hematopoietic stem cells and characterized by the presence of primitive or atypical myeloid or lymphoid cells in the bone marrow and the blood. "Plag1 and its homologue, Plagl2, have also previously been implicated in leukemia, being observed as candidate cooperating oncogenes in a retroviral insertion screen with the CBFβ-MYH11 product of the inv16 gene rearrangement." (PMID 30890554, 2019). "Bulk-transduced populations were transplanted into recipient mice to generate primary murine leukemias and determine if coexpression of Plag1 or Lin28b would phenocopy Ezh2 loss and accelerate AML onset in comparison with MLL-AF9 alone." (PMID 30890554, 2019). "In contrast, Plag1 overexpression with MLL-AF9 profoundly accelerated the development of leukemia compared with the MLL-AF9 control arm (P < 0.0001)." (PMID 30890554, 2019). "Moreover, neither expression of Plag1 nor Lin28b was significantly altered following GSK343 treatment of MLL-AF9 tumors, reinforcing the concept of disparity between transcriptional programs repressed by Ezh2 that are responsible for early tumor suppression and later maintenance of these leukemias." (PMID 30890554, 2019).
lung carcinoma (3 papers, 2022 to 2025). "The results showed that the expression of PLAG1 in lung cancer tissues was significantly higher than that in adjacent tissues (the difference between the means was 1.408 ± 0.4914, p = 0.0053)." (PMID 36249072, 2022). "MiR-21 regulated lung cancer cells directly via the Wnt/-catenin pathway, and let-7 exerted its effects via the PLAG1/GDH1 pathway." (PMID 36249072, 2022). "The activation of PLAG1 might be the critical event in the development of multiple human cancers; for example, upregulation of PLAG1 was found in anoikis-resistant lung cancer cell lines and was required for lung metastasis." (PMID 36600208, 2023). "We used qRT-PCR to determine the expression of PLAG1 in 42 cases of lung cancer." (PMID 36249072, 2022). "We found that upregulation of let-7 suppressed the expression of PLAG1, while PLAG1 could promote apoptosis resistance and metastasis of lung cancer by regulating glutamate dehydrogenase 1 (GDH1)." (PMID 36249072, 2022). "Therefore, upregulation of let-7 suppressed PLAG1, which targets GDH1 to inhibit lung cancer cells." (PMID 36249072, 2022).
melanoma (3 papers, 2022 to 2025). A malignant, usually aggressive tumor composed of atypical, neoplastic melanocytes. "Moreover, we constructed a miRNA–miRNA interaction network using the miRNet tool, revealing key regulatory genes in melanoma, including PLAG1, TGFBR2, CDKN2A, MAPK14 and MYC, which exhibited significant degrees and betweenness centrality in the network analysis." (PMID 39823244, 2025).
mucoepidermoid carcinoma (3 papers, 2017 to 2024). A carcinoma morphologically characterized the presence of cuboidal mucous cells, goblet-like mucous cells, squamoid cells, cystic changes, and a fibrotic stromal formation. "Furthermore, mucoepidermoid carcinoma involves a MAML2 gene fusion, whereas MECA is associated with a PLAG1 gene rearrangement." (PMID 39479012, 2024).